KL (klotho)
Diseases named in the same sentence as KL in open-access papers (continued):
Sharing a sentence is not in itself a finding about the gene and the disease.
chronic obstructive pulmonary disease (17 papers, 2017 to 2025). A chronic and progressive lung disorder characterized by the loss of elasticity of the bronchial tree and the air sacs, destruction of the air sacs wall, thickening of the bronchial wall, and mucous accumulation in the bronchial tree. "Loss of soluble Klotho promotes cardiac arrhythmia owing to decreased activity of the KCNQ1/KCNE1 channels in cardiomyocytes." (PMID 35406743, 2022). "Chronic obstructive pulmonary disease (COPD) is associated with the downregulation of Klotho expression in the airways and an increase in circulating FGF23 levels." (PMID 32188018, 2020). "Klotho expression is decreased in the lungs of smokers and further reduced in patients with chronic obstructive pulmonary disease (COPD) which is associated with increased oxidative stress, inflammation and apoptosis." (PMID 31346213, 2019). "Several studies have reported the anti-inflammatory effects of Klotho in cultured cells and an association between a reduction of Klotho and the inflammatory response in chronic obstructive pulmonary disease and renal injury." (PMID 29403373, 2017). "Nevertheless, a recent study examined the relationship between plasma klotho levels and the clinical condition of patients with chronic obstructive pulmonary disease who participated in a three-week pulmonary rehabilitation program." (PMID 38541889, 2024). "Klotho counteracts cardiac arrhythmia by ensuring the cell surface expression of KCNQ1/KCNE1 K+ channels that are involved in cardiac repolarization." (PMID 35406743, 2022). "α-klotho (KL) is an anti-aging protein and has been shown to exert anti-inflammatory and anti-oxidative effects in the lung and pulmonary diseases such as chronic obstructive pulmonary disease (COPD) and cystic fibrosis." (PMID 32039219, 2019). "Klotho is an anti-aging protein that has multiple functions and may play a key role in the pathogenesis and progression of chronic respiratory diseases such as chronic obstructive pulmonary disease (COPD)." (PMID 38287280, 2024). "Klotho may either be overexpressed, which extends lifespan in model organisms, or disrupted, which accelerates systemic aging phenotypes (e.g., arterial stiffness, atherosclerosis, chronic obstructive pulmonary disease, infertility, premature mortality)." (PMID 37580799, 2023). "However, the relationship between imbalanced FGF23-Klotho axis and the development of cardiac arrhythmias in CKD remains unknown." (PMID 35042527, 2022). "Moreover, investigations have revealed a significant reduction in muscle mass in mice lacking the klotho protein, as well as a positive correlation between klotho levels and muscle mass in individuals with chronic obstructive pulmonary disease." (PMID 38907289, 2024).
gastric cancer (17 papers, 2013 to 2025). A primary or metastatic malignant neoplasm involving the stomach. "Our findings revealed that downregulation of KL gene expression promotes cell proliferation and contributes to the progression of gastric cancer." (PMID 37915566, 2023). "For instance, circ-ITCH affects the EMT pathway and suppresses metastasis of gastric cancer by sponging miR-199a-5p and thereby increasing Klotho expression." (PMID 35327551, 2022). "In gastric cancer, circITCH suppresses cancer metastasis via acting as an miR‐199a‐5p sponge and increasing Klotho levels." (PMID 35274492, 2022). "Treating gastric cancer cells with the demethylating reagent 5-Aza restored Klotho expression, increasing the ratio of LC3-II/LC3-I, indicating activation of autophagy." (PMID 34737707, 2021). "The human sex determining region Y (SRY)–related high-mobility-group (HMG) box protein family member 17 (SOX17) protein also binds to the KL promoter in gastric cancer cells, thereby inducing KL expression." (PMID 33520985, 2020). "KL promoter hypermethylation with decreased gene expression is typical of gastric carcinomas and gastric carcinoma cell lines." (PMID 33520985, 2020). "miR-199a-5p has been shown to function as an oncogene in gastric cancer cells partially through targeting klotho, which can suppress invasiveness and epithelial-mesenchymal transition." (PMID 26717044, 2016). "In this study, we investigated the involvement of klotho in gastric cancer cell proliferation, apoptosis, and autophagy as well as the associated signaling." (PMID 23432957, 2013). "Klotho is a tumor suppressor in gastric cancer, which regulates IGF-1R phosphorylation and the subsequent activation of IRS-1/PI3K/Akt/mTOR signaling, tumor cell proliferation, apoptosis, and autophagy." (PMID 23432957, 2013). "Klotho is a recently identified tumor suppressor gene that epigenetically inactivated in gastric cancer." (PMID 23432957, 2013). "Among the 3 tested gastric cancer cells, GC-7901 showed the lowest expression of klotho mRNA and protein and highest level in methylation of klotho promoter." (PMID 23432957, 2013). "The Klotho gene has been demonstrated to be a tumor suppressor in several tumors, including gastric cancer." (PMID 23432957, 2013). "Similar to pancreatic cancer, miR-199a influences KL expression in gastric cancer." (PMID 33520985, 2020). "Moreover, miR-199a-5p overexpression promoted cell migration and invasion by targeting klotho in gastric cancer cells." (PMID 27814720, 2016). "However, the signaling pathways involved in the suppressive role of klotho have rarely been reported in gastric cancer." (PMID 23432957, 2013). "In conclusion, KL acts as a novel tumor suppressor gene that is epigenetically silenced in gastric cancer, and KL promoter could serve as a valuable predictor of prognosis for gastric cancer patients." (PMID 40004457, 2025). "KL overexpression inhibits growth and ERK1/2 activity, resulting in apoptosis of AGS and MKN28 gastric carcinoma cells." (PMID 33520985, 2020). "Our previously studies found that Klotho protein inhibited the activation of IRS-1 / PI3K / Akt / mTOR and ERK / p70s6k and downstream signaling pathways in gastric cancer and liver cancer cells, mainly through the inhibition of IGF-1R phosphorylation." (PMID 27779100, 2016). "The mRNA expression of klotho gene was detected by RT-PCR and obviously lower klotho expression was observed in MNK-45, AGS, and GC-7901 gastric cancer cells than in the GES-1 normal gastric epithelial cells." (PMID 23432957, 2013). "Methylation of klotho gene promoter in GC-7901, MNK-45 and AGS gastric cancer cells as well as GES-1 normal gastric epithelial cells was detected by bisulfate-based PCR." (PMID 23432957, 2013). "However, the signaling pathways involved in the tumor suppressive roles of klotho in gastric cancer cells have not been clearly elucidated." (PMID 23432957, 2013).
Sepsis (17 papers, 2018 to 2026). Sepsis is defined as life-threatening organ dysfunction caused by a dysregulated host response to infection. "A previous study reported that klotho deficiency aggravates sepsis-related multiple organ dysfunction." (PMID 33329595, 2020). "Additionally, a previous study reported that klotho deficiency aggravates sepsis-related multiple organ dysfunction." (PMID 33329595, 2020). "Interestingly, Klotho deficiency aggravates experimental sepsis-related multiorgan function, and it has been proposed that Klotho reduction may be a pathogenic factor, promoting inflammation, senescence, and maladaptive recovery following AKI." (PMID 37892163, 2023). "In a similar manner, our findings indicated that the downregulation of klotho following sepsis was ameliorated by CLM, resulting in the inactivation of NLRP-3." (PMID 40770673, 2025). "As shown in these figures, the expression levels of RETN, S100A12, IL18R1, and KL were higher in the sepsis group, while that of GZMB, HLA-DPA1, CD3E, IL2RB, CD3G, and CCR3 were higher in the normal group (p < 0.05)." (PMID 38124071, 2023). "It is interesting to note that the lipopolysaccharide (LPS) injection-induced sepsis model showed decreased KL mRNA expression." (PMID 38124071, 2023). "Our findings showed that the expression of RETN, S100A12, IL18R1, and KL was higher in the sepsis group, while the expression of GZMB, HLA-DPA1, CD3E, IL2RB, CD3G, and CCR3 was higher in the control group." (PMID 38124071, 2023). "Renal Klotho deficiency is found in many types of AKI such as that induced by ureteral obstruction, lipopolysaccharide (model of sepsis), nephrotoxins including cisplatin, and folic acid." (PMID 29725301, 2018). "Similarly, administration of recombinant Klotho in septic mice alleviated sepsis-induced AKI by activating Nrf2 to inhibit the ferroptosis signaling pathway." (PMID 38786957, 2024). "Autophagy activation was observed after CLP, while the protective effect developed by Klotho in sepsis-induced AKI might be irrelevant to autophagy." (PMID 37215112, 2023). "As a systemic inflammatory response to infection, various inflammatory factors significantly increase in cases of sepsis, and these inflammatory cytokines may contribute to the reduced klotho expression in the kidney." (PMID 31309036, 2019). "We note that sepsis shock syndrome represents loss of regulation of inflammatory response to infection and that vitamin D, parathyroid hormone, fibroblast growth factor, and klotho interact with sepsis defense mechanisms in which movement of calcium and phosphorus are part of the process." (PMID 30134544, 2018). "The combined FEK indicator, including Fibroblast Growth Factor 23, erythropoietin, and Klotho, predicted the development of AKI, short-/long-term mortality, and one-year CKD progression in critical care patients with sepsis." (PMID 37892163, 2023). "Nevertheless, reduced Klotho protein expression is one of the most likely scenarios for the renal FGF23 resistance observed in septic patients and experimental sepsis models." (PMID 33989306, 2021). "We hypothesized that a combined indicator that includes plasma FGF23, EPO, and Klotho would predict the development of AKI, mortality, and long-term CKD progression in sepsis patients." (PMID 37892163, 2023). "FGF23 signaling requires the presence of the co-receptor Klotho and there is convincing evidence that renal Klotho protein expression is reduced in septic patients with AKI, in septic foals, and in experimental sepsis models." (PMID 33989306, 2021). "Interestingly, Klotho depletion has also been shown to mediate AKI in a variety of conditions including acute myocardial infarction, rhabdomyolysis, COVID-19, and sepsis, as well as platinum and vancomycin toxicity." (PMID 38786957, 2024).
Sepsis (continued). "Therefore, we performed a prospective study with sepsis patients in order to explore early biomarkers for AKI prediction at hospital admission and these biomarkers included measurements of glomerular function (cystatin C), proximal and distal tubule function (KIM-1 and klotho)." (PMID 35272698, 2022).
colon carcinoma (16 papers, 2015 to 2025). "So, in this sense, a reduction in the expression of the Klotho gene is linked to malignancy formation in different cancers, such as colon cancer." (PMID 40004457, 2025). "Loss of Klotho contributes to kidney injury by de-repression of Wnt/β-catenin signaling and similar mechanisms may be active in colon cancer cells." (PMID 28060743, 2017). "This study explored the downstream effects of overexpressing the Klotho gene, which has an antitumor effect on resistant human colon cancer cells, focusing on its action on TRAIL death and decoy (DcR1 and DcR2) receptors." (PMID 40004457, 2025). "The analysis of Klotho protein expression in our study revealed that quercetin stimulated the expression of Klotho in colon cancer cells, promoting tumor-suppressing activity." (PMID 36807774, 2023). "Further, quercetin also modulates the expression of anti-aging genes SIRT-6 and Klotho to inhibit colon cancer cell proliferation." (PMID 36807774, 2023). "Quercetin arrested colon cancer cell growth by modulating expression of aging proteins including Sirtuin-6 and Klotho and also by inhibiting telomerase activity to restrict the telomere length which is evident from qPCR analysis." (PMID 36807774, 2023). "used CRISPR to up-regulate Klotho gene in colon cancer cell Caco-2, and found that cell proliferation was inhibited and tumorigenic recovery was achieved, confirming that Klotho gene can promote tumor cell apoptosis." (PMID 37020597, 2023). "In colon cancer cells transduced with a Klotho lentiviral construct, the investigators showed that Klotho downregulates the expression of IGF-1, PI3K, and AKT (mRNA and protein), with subsequent inhibition of growth and invasion of colon cancer cells." (PMID 32585905, 2020). "Accumulated evidence indicates that Klotho acts as tumor suppressor in many cancer cell types, such as pancreas cancer, colon cancer, and hepatoma." (PMID 32899868, 2020). "Epigenetic silencing through KL promoter hypermethylation is observed in different colon cancer cell lines." (PMID 33520985, 2020). "Our previous work has shown that Klotho is silenced, or significantly down‐regulated in colon cancer cells by DNA hypermethylation in its promoter region." (PMID 31545552, 2019). "In this regard, Klotho suppresses growth and invasion of colon cancer cells through inhibition of the IGF1R-mediated PI3K/Akt pathway and is frequently inactivated through promoter hypermethylation in CRC." (PMID 28060743, 2017). "Klotho has been shown to regulate intestinal barrier function and protect against gut inflammation, which may help to prevent the development of colon cancer." (PMID 38069256, 2023). "A comprehensive dataset revealed that frequent hypermethylation of Klotho promoter results in poor expression of Klotho in colon cancer cells and suggests that DNA methylation alterations could serve as biomarkers for colon cancer." (PMID 36807774, 2023). "Furthermore, Klotho has been shown to be down-regulated through promoter methylation in 83.3% of colon cancer cell lines and 85% of primary colorectal cancer tissues." (PMID 32585905, 2020). "Klotho can inhibit colon cancer cell growth and their apoptosis." (PMID 31545552, 2019). "Thus, we examined the activation status of ERK1/2 in KL overexpressed colon cancer cells, and observed a decrease in the activation of ERK1/2." (PMID 29884183, 2018). "In human colon cancers, expression of Klotho was downregulated and correlated with tumor invasion and Dukes staging, while overexpression of Klotho inhibited cell proliferation and invasion through inhibition of IGF1R-mediated PI3K/AKT pathway in colon cancer cells." (PMID 26499380, 2015).
colon carcinoma (continued). "In addition to the regulation of aging-associated miRNA and anti-aging protein activity such as Klotho and SIRT-6, inhibition of telomerase activity leading to the shortening of telomere length paved an interesting avenue towards future designing of colon cancer therapeutics." (PMID 36807774, 2023). "Remarkably, enhanced Klotho expression curtailed both tumor growth and invasion by impeding the IGF1R-mediated PI3K/Akt pathway in colon cancer cells." (PMID 40004457, 2025). "Overexpression of KL or KL1 fragment or treatment with sKL decreases surviving colonies and cell proliferation and induces cell cycle arrest and apoptosis of colon cancer cells." (PMID 33520985, 2020). "In the end, we measured the ECAR in ERK2E322K/KL overexpression colon cancer cells, and demonstrated that ERK2E322K overexpression increased the ECAR value in KL overexpressed cells (P < 0.05), suggesting the role of ERK on KL mediated glycolysis regulation." (PMID 29884183, 2018). "It has reported that overexpression of Klotho inhibits growth and invasion through inhibition of IGF1R-mediated PI3K/AKT pathway in colon cancer cells." (PMID 26499380, 2015). "The expression level of Klotho was seen to be significantly increasing in quercetin-treated colon cancer cells, In HCT 116, the expression of Klotho was significantly increased in HQ80μM (***p = 0.001) and HQ120μM (***p < 0.001) compared to the HCT 116 control group." (PMID 36807774, 2023). "Our previous studies demonstrated that KL played negative roles in colon cancer cell proliferation and metastasis." (PMID 29884183, 2018). "To determine whether KL regulated HIF1α, we overexpressed constitutive active form of ERK-MAPK kinase ERK2 (ERK2E322K) into colon cancer cells." (PMID 29884183, 2018). "However, in tumour studies Klotho has been shown to have antiproliferative effects, decreasing PCNA expression in colon cancer cells, and we hypothesise it may be protective during the acute phase of IRI." (PMID 28129785, 2017).